SIRT1 (sirtuin 1)
Diseases named in the same sentence as SIRT1 in open-access papers (continued):
Sharing a sentence is not in itself a finding about the gene and the disease.
Sepsis (continued). "Furthermore, pharmacological SIRT1 activation decreased mortality in experimental sepsis." (PMID 28003866, 2016). "Thus, our results suggest that SIRT1 or SIRT1 expression-inducing cytokines may be useful targets for pharmacological drug development to protect against sepsis." (PMID 24573134, 2014). "Interestingly, Sirt1 expression is reduced during aging and in some pre-existing inflammatory diseases such as COPD and alcoholic fatty liver disease, and the elderly are also highly susceptible to inflammatory disorders including sepsis." (PMID 24896770, 2014). "This interaction further activates the SIRT1/PGC-1α/Nrf2 signaling pathway, leading to the inhibition of cellular focal death and the mitigation of sepsis-induced kidney injury." (PMID 40657645, 2025). "Furthermore, SIRT1 deficiency promotes excessive mtROS generation and mtDNA leakage into the cytoplasm by impairing late endosome-mediated mitochondrial autophagy, leading to enhanced activation of NLRP3 and STING, which results in pulmonary endothelial dysfunction in sepsis." (PMID 40766066, 2025). "Cumulatively, the finding of this study suggests that 3,4‐cPP upregulates SIRT1 by continuously activating S1P1, suppressing proinflammatory immune responses and preventing endothelial cell damage, protecting against sepsis." (PMID 40470379, 2025). "Mechanistic studies revealed that adiponectin attenuates inflammatory responses in macrophages through both Sirtuin 1 (SIRT1)-dependent and independent pathways, suggesting a broader regulatory role in immune function during sepsis." (PMID 40652274, 2025). "Collectively, 3,4‐cPP maintains endothelial integrity via the SIRT1/HPA‐1/HSPG pathway, mitigating sepsis." (PMID 40470379, 2025). "A growing body of evidence supports the critical role of SIRT1, the highly conserved NAD+-dependent deacetylase, in the development of the sepsis process." (PMID 40698661, 2025). "Both SIRT1 and SIRT2 can dampen the inflammatory responses of endothelial cells during sepsis through deacetylation, reducing the secretion of NF-κB-dependent adhesion molecules." (PMID 38690282, 2024). "In our study, we found originally the protective function of taraxerone against sepsis-induced ALI in mice and further investigated the effect of taraxerone via SIRT1 to determine the mechanism of its anti-inflammatory and anti-oxidative stress effects." (PMID 39543653, 2024). "SIRT1 upregulation reduces PKM2 acetylation, preventing its nuclear accumulation and alleviating inflammatory responses in sepsis-induced alveolar epithelial cells." (PMID 38690282, 2024). "In the intricate immune-metabolic landscape of sepsis, the AMPK/SIRT1/PGC-1α axis orchestrates a pivotal regulatory network that modulates cellular inflammatory responses." (PMID 38690282, 2024). "Sirtuin1 (SIRT1) is an NAD-dependent protein deacetylase, which is considered the main regulator of sepsis-induced acute kidney injury because it reduces oxidative stress and inflammation." (PMID 37628912, 2023). "mRNA expressions of Nuclear Respiratory Factor 1 (Nrf1), Mitochondrial transcription factor A (Tfam), and Silent mating type information regulation 2 homolog 1 (Sirt1)—regulators of biogenesis—remained unchanged between groups (SPF vs. SF and Sepsis vs. SPF)." (PMID 37106730, 2023). "Eight genes (CLEC5A, MALT1, NAIP, NLRC4, SERPINB1, SIRT1, STAT3, and TLR2) related to sepsis diagnosis were screened by multiple machine learning algorithms." (PMID 36817458, 2023). "It was demonstrated that SIRT1 reduces H3K16 acetylation and inhibits TNF-α transcription during sepsis-induced inflammation by targeting the TNF-α promoter." (PMID 36774341, 2023). "In LPS cell models and CLP-induced sepsis mouse models, deacetylation of HMGB1 achieved by activating SIRT1 reduces the release of HMGB1 and sepsis-related mortality." (PMID 37628912, 2023). "Thus, SIRT1 activation might be beneficial against injury in sepsis." (PMID 37475042, 2023).
Sepsis (continued). "SIRT1, an NAD + dependent histone deacetylase, is considered to be one of the major regulatory molecules of sepsis induced acute kidney injury due to its role in reducing oxidative stress and inflammation." (PMID 38259279, 2023). "The available data show that under severe stress in sepsis, sustained NAD+ production and increased SIRT1 expression and activation maintain an adaptive phenotype." (PMID 37371959, 2023). "Both PD and RES are potent activators of sirtuin 1 (SIRT-1) that plays a vital role in protecting the small intestine, reduces microvascular inflammation, and limits systemic injury due to sepsis." (PMID 35955576, 2022). "Differential analysis of SIRT1, TLR2, and HSP90AA1 in the sepsis liver injury-control group (SLi-C), p-value were all <0.05, and differential expression." (PMID 36406124, 2022). "Our study suggests that NAD+ supplementation contributed to rescued the renal damage and its deficits increased vulnerability to sepsis‐induced AKI, which performed in a SIRT1‐dependent manner." (PMID 35137552, 2022). "We have shown differential roles of SIRT1 and SIRT2 in sepsis in a biological context-dependent manner previously." (PMID 36865524, 2022). "emodin alleviates sepsis-mediated ALI via inhibition and reduction of NF-kB and HMGB1 pathways mediated by SIRT1." (PMID 35720285, 2022). "The benefit effect of melatonin on SIRT1 activation was considerably blocked by luzindole and slightly blocked by 4P-PDOT in small intestine 8 h following sepsis." (PMID 33790896, 2021). "Increased glycolysis during the early inflammatory phase of sepsis results in high concentration of NAD+, which induces SIRT6 and SIRT1 activity." (PMID 34828304, 2021). "Hence, we speculated that miR-9-5p interacted with SIRT1 to affect sepsis." (PMID 34743197, 2021). "Previous studies have fully explored the role of Sirt1 in sepsis-induced ARDS/ALI, and they found that Sirt1 protects lung from inflammation." (PMID 34630854, 2021). "For example, inhibitors of histone deacetylases sirtuin-1 and sirtuin-2 (SIRT1/2) have shown the capacity to reverse immune paresis in experimental murine sepsis." (PMID 33868313, 2021). "Generally speaking, our study has manifested that in sepsis-mediated lung injury, OIP5-AS1/miR-128-3p/SIRT1 plays a vital role by suppression of phosphorylation of NF-κB and the release of pro-inflammatory factors." (PMID 34592882, 2021). "SIRT1 and SIRT6 have a major role on the regulation of the acute inflammatory response during sepsis by controlling the transition from an early inflammatory response to a late stage where immune cells enter in a resting state and resolve the infection." (PMID 34828304, 2021). "Substantial evidence indicated the SIRT1-modulated deacetylation of HMGB1 alleviated inflammation, restored renal function, and prolonged the survival time of mice with sepsis-related acute kidney injury." (PMID 34906140, 2021). "In this study, a mouse model of sepsis-induced AKI, generated by cecal ligation and puncture operation, was used to investigate the protective effects of THC and the role of SIRT1." (PMID 34187277, 2021). "In a mouse model of sepsis and in LPS-stimulated macrophages, the expression of lncRNA-CCL2 is increased dramatically, while that of Sir2 homolog (SIRT1) is decreased." (PMID 35011565, 2021). "It was observed that TUG1 was downregulated in sepsis and overexpression of TUG1 targets the axis of miR-142-3p/sirtuin 1 and regulates the NF-kB pathway to suppress disease progression." (PMID 34872438, 2021). "SIRT1, an NAD+-dependent protein deacetylase, is regarded as a major modulator of sepsis-induced AKI for its role in mitigating oxidative stress and inflammation." (PMID 34187277, 2021).
Sepsis (continued). "Melatonin reportedly alleviates sepsis-induced multi-organ injury by inducing autophagy and activating class III deacetylase Sirtuin family members (SIRT1–7)." (PMID 33790896, 2021). "For example, miR‐30a inhibits proliferation and promotes apoptosis of hepatocytes via targeting SOCS‐1 in sepsis rats and MCPIP1‐controlled miR‐9 is involved in septic liver injury by regulating SIRT1 expression." (PMID 32369227, 2020). "For instance, miR‐30a suppresses proliferation and increases apoptosis of hepatocytes by regulating SOCS‐1‐mediated JAK/STAT pathway in sepsis rats, and MCPIP1‐regulated miR‐9/SIRT1 axis is involved in LPS‐induced liver injury." (PMID 32369227, 2020). "SIRT1 is a NAD+ dependent deacetylase, and involved in the protective effect of melatonin on multiple organs during sepsis." (PMID 33362546, 2020). "More importantly, SIRT1 negatively correlated with SOFA score (r=-0.458) and APACHE II score (r=-0.526) (all P<0.05) in sepsis patients." (PMID 33263643, 2020). "SIRT1 negatively correlated with Scr (r=-0.236), WBC (r=-0.202), and CRP (r=-0.405) and positively correlated with albumin (r=0.416) in sepsis patients." (PMID 33263643, 2020). "These pathways are potentially targetable: inhibitors of the histone deacetylases sirtuin 1 and 2 (SIRT1/2) have shown efficacy in reversing immune paralysis in mouse models of sepsis." (PMID 30804947, 2019). "Decreased SIRT1/SIRT3 protein levels correlate with increased glycolysis and its adverse effect on cardiac dysfunction during early sepsis." (PMID 30216989, 2018). "We further highlight the role of SIRT1 and SIRT2 as potential “druggable” targets for promoting immunometabolic homeostasis and increasing sepsis survival." (PMID 30216989, 2018). "Our results indicate that SIRT1 inhibits Notch signaling through NICD deacetylation and thus ultimately alleviates sepsis." (PMID 29867921, 2018). "However, the protective effects of BML-111 in sepsis-induced neuroinflammation and cognitive impairment are unknown, and so in this study we hypothesized that BML-111 reduces neuroinflammation and cognitive impairment induced by sepsis via the SIRT1/NF-κB signaling pathway." (PMID 30186119, 2018). "Pharmacological activation of SIRT1 shows potential for the treatment of sepsis since PGC‐1α expression was found to be severely downregulated in muscle of septic mice, while SIRT1 activation proved to increase survival in the CLP sepsis model." (PMID 29976786, 2018). "We demonstrated sustained increase in SIRT1 and SIRT3 protein levels during the hypo-inflammatory phase of sepsis in which fatty acid oxidation replaces glycolysis as the predominant fuel source." (PMID 30216989, 2018). "In contrast with SIRT1 and SIRT2, SIRT5 expression is decreased during the hypo-inflammatory phase of sepsis." (PMID 30216989, 2018). "The sirtuin family consists of sirtuins 1–7; among them, sirtuin 1 (SIRT1) is the most studied one, during the development of sepsis." (PMID 30533222, 2018). "We have also shown that SIRT1 directly or indirectly influences the expression of SIRT 3 and 6 in sepsis, as reviewed in the respective sections." (PMID 30216989, 2018). "Sepsis increased NF-κB activation and HMGB1 nucleocytoplasmic translocation and iNOS protein expression, but decreased SIRT1 protein expression in lung tissues." (PMID 28931916, 2017). "A murine sepsis model in C57BL/6 mice injected with LPS stimulated TLR4 and activated SIRT1, which induced NF-κB p65 deacetylation and deactivation thus inhibiting pro-inflammatory gene expression." (PMID 28579962, 2017). "In this study, we used a septic rat model to determine the effects of SIRT1 and SIRT3 on acute kidney injury (AKI) following sepsis." (PMID 28003866, 2016).
Sepsis (continued). "Furthermore, SIRT1, which encodes a histone deacetylase essential to nuclear–mitochondrial communication during immune–metabolic adaptation in sepsis, and which modulates epigenetic gene silencing in endotoxin tolerance, was downregulated in patients with SRS1 and has a sepsis cis-eQTL." (PMID 26917434, 2016). "We observed reduced SIRT1/3 activity, elevated acetylated SOD2 (ac-SOD2) levels and oxidative stress, and damaged mitochondria in RTECs following sepsis." (PMID 28003866, 2016). "We discovered that in cell and lean mouse models of sepsis that nuclear SIRT-1 couples with nuclear NFκB p65/ RelB, nuclear SIRT-6 and mitochondrial SIRT-3 as homeostasis checkpoints during acute sepsis-inflammation." (PMID 27500833, 2016). "Of particular interest is the possibility that the acetylation-dependent interaction of SIRT1 and HMGB1 participates in the pathophysiology of sepsis." (PMID 26522327, 2015). "In our study, the SIRT1 inhibitor EX527 and taraxerone were used successively to treat mice and primary macrophages, and the results showed that EX527 blocked taraxerone-inhibited sepsis-induced or LPS-induced elevated ROS levels." (PMID 39543653, 2024). "In addition, Sirt1 is involved in PINK1/Parkin-related activation of mitochondrial autophagy and inhibits apoptosis and scorching of RTECs, thereby reducing sepsis-induced AKI." (PMID 38347622, 2024). "Furthermore, Zeng and associates discovered that lncRNA GAS5 forms a regulatory axis with miR-155-5p/SIRT1/HMGB1 in sepsis, with lncRNA GAS5 upregulating SIRT1 to suppress HMGB1 acetylation and release." (PMID 38690282, 2024). "Sirtuin 1 (SIRT1), a deacetylase, has received widespread recognition in sepsis." (PMID 38540968, 2024). "Based on our data, the combination of SIRT1 and FTO inhibitors which contribute to m6A methylation increases might be an effective therapeutic approach for the prevention or management of sepsis and COVID-19 in clinic." (PMID 36864027, 2023). "Moreover, the protective effects of echinacoside against sepsis-induced ALI and lung oxidative stress were blocked by EX527, a SIRT1 inhibitor." (PMID 38001778, 2023). "Thus, BAM15 appears to activate AMPK during the early phase of sepsis-AKI and activates SIRT1 during the late phase of sepsis-AKI; this is followed by increasing mitochondrial biogenesis associated with PGC1α activation." (PMID 36757801, 2023). "Since NAD+ is an important antioxidant mechanism by directly balancing the redox status and/or indirectly promoting SIRT1/3-mediated antioxidant defences, decreased NAD+ may promote mitochondrial dysfunction and organ injury in sepsis through SIRT3 inhibition." (PMID 38057866, 2023). "For example, Sirtuin 1 (SIRT1), a NAD+-dependent histone deacetylase and transcriptional enhancer of GR, has been found to restrain lung inflammasome activation in a murine model of sepsis." (PMID 35279129, 2022). "Therefore, the role of increased amounts of SIRT1 substrate, NAD+, cannot be simply defined as beneficial or detrimental in sepsis." (PMID 36139711, 2022). "The expression of SIRT1 protein was not affected by anemia, blood transfusion, sepsis, parity, NICU, mechanical ventilation, CHD, Apgar score (1 min), and neonatal asphyxia in 43 children diagnosed with NEC." (PMID 35958178, 2022). "Similarly, a cross talk between SIRT1 and SIRT2 during acute ethanol-induced immunosuppression in ethanol with sepsis, needs evaluation." (PMID 36865524, 2022). "Furthermore, melatonin also upregulated SIRT1 in cardiomyocytes, whereas EX527 inhibition of SIRT1 abrogated the cardioprotective effects of melatonin in sepsis." (PMID 35795371, 2022). "The study, therefore, sheds light on the mechanisms underlying the renoprotective capacity of NAD+ and identifies NAD+/SIRT1/GSK‐3β/Nrf2 pathway as a potential therapeutic target, which might be used to prevent or ameliorate sepsis‐induced AKI." (PMID 35137552, 2022).
Sepsis (continued). "miR-29a expression is positively correlated with septicemia myocardial injury, and overexpression of lncRNA CRNDE guards against the oxidative damage and apoptosis of myocardial tissues by hindering the miR-29a/SIRT1 axis." (PMID 35599576, 2022). "Indeed, in a model of sepsis, NAD+ levels have been shown to regulate a metabolic shift in macrophages from glycolytic metabolism to increased FAO by a mechanism involving SIRT1 and SIRT6." (PMID 34828304, 2021). "PCTR1 protects endothelial glycocalyx via ALX receptor by regulating SIRT1/NF-κB pathway, suggesting PCTR1 may be a significant therapeutic target for sepsis-related acute lung injury." (PMID 34217286, 2021). "The nuclear SIRT1 and mitochondrial SIRT3 regulate mitochondrial biogenesis during sepsis." (PMID 35052507, 2021). "The aim of the present study was to explicate the protective roles of THC in the setting of sepsis-induced AKI and to investigate whether its positive effects are connected with the activation of SIRT1 signaling." (PMID 34187277, 2021). "We showed both SIRT1 and SIRT2 deacetylate NFκB p65 subunit in sepsis." (PMID 35052507, 2021). "Critically, nicotinamide riboside has been shown in experimental models of murine sepsis to limit both pulmonary and cardiac toxicity, likely through NAD+/SIRT1 signaling, suggesting that this may be a key factor influencing outcomes in our CLP model." (PMID 34512866, 2021). "When SIRT1 is activated in cecum ligation and puncture (CLP) models and LPS-induced cell lines, the expression, translocation, and release of HMGB1, which are the most important factors in sepsis, decreased." (PMID 34445236, 2021). "However, in most studies, increasing the Sirt1 level would benefit BBB damage after oxygen glucose deprivation, subarachnoid hemorrhage or sepsis-induced brain injury." (PMID 32381096, 2020). "SIRT1, an NAD+-dependent class III histone deacetylase, is mainly localized in the nucleus, and it modulates the immune and inflammatory responses of sepsis to control inflammatory injury in multiple organs, and ultimately protect against multiple organ dysfunction." (PMID 33263643, 2020). "Despite up-regulation of Nrf2 (1.54-fold increase) and HO-1 (1.82-fold increase) expressions in lung tissues, the lack of increase in SIRT1 expression was shown in sepsis group (0.66-fold decrease)." (PMID 32903604, 2020). "Second, SIRT1 level of sepsis patients was only detected before antibiotic therapy and the variation of SIRT1 during the antibiotic therapy was not considered." (PMID 33263643, 2020). "Similarly, resveratrol, a specific SIRT-1 agonist, has been shown to upregulate SIRT-1 expression and protect against cerebral IR injury, radiation-induced intestinal injury, and sepsis-induced myocardial injury." (PMID 31028246, 2019). "SIRT1 may also promote the repressor phenotype of CD4+Fox3p+ TReg cells, which are known to increase during sepsis." (PMID 30069485, 2018). "However, SIRT5 showed opposite expression patterns and functions compared with SIRT1 and SIRT2 in a sepsis model involving macrophages." (PMID 30533222, 2018). "However, due to the large individual differences in the time window of the inflammatory response after sepsis, administration of the SIRT1 activator, SRT1720, should insure that SIRT1 exerts a beneficial effect in a timely manner." (PMID 30533222, 2018). "The differential changes in CD80 and CD86 expression on CD11c+ DCs during the early and late phases of our sepsis model suggest that CD80+ and CD86+ are differentially modulated due to sepsis, so we determined whether SIRT1 inhibition balances this pattern." (PMID 30069485, 2018). "In addition, nuclear SIRT1 can guide RELB to differentially induce SIRT3 expression, and it also can increase mitochondrial biogenesis, which alters bioenergetics during sepsis adaptation." (PMID 30533222, 2018).